INS (insulin)
Diseases named in the same sentence as INS in open-access papers (continued):
Sharing a sentence is not in itself a finding about the gene and the disease.
Insulin resistance (continued). "Thus, the db/db mice show the characteristic obesity and enormous appetite; hyperinsulinemia, insulin resistance, and hyperglycemia occur at the age of 2-4 weeks; the secretory function of β-cells gradually declines around the age of 4-6 months and the mice exhibit an absolute deficiency in insulin." (PMID 30050584, 2018). "Ours is the first study to assess the effect of intranasal insulin on LH concentrations in men with type 2 diabetes, a population that has insulin resistance and a high prevalence of HH." (PMID 30515210, 2018). "In this experiment, feeding mulberry leaf water solution (80 mg/kg) to diabetic mice significantly reduced fasting blood glucose (FBG) and increased serum insulin levels, resulting in reduced insulin resistance and improved insulin receptor sensitivity." (PMID 30131712, 2018). "The change in glucose metabolism correlated strongly with the change of insulin resistance and insulin secretion after SSA treatment." (PMID 29853879, 2018). "The patients who followed the diet also significantly improved their basic biochemical parameters in the blood: AST, ALT, total cholesterol, HDL, insulin concentration, and insulin resistance." (PMID 30631760, 2018). "The HOMA-IR index is a measure of insulin sensitivity—it has low values indicating optimal insulin sensitivity and high values corresponding to different degrees of insulin resistance." (PMID 29770126, 2018). "In the present study, Metrnl was found to be correlated with insulin resistance and the parameter of glucose and insulin metabolism in T2DM patients." (PMID 30212581, 2018). "In this study, the HFD mice had elevated fasted blood glucose (p = 0.05), and HOMA-IR values (representing insulin resistance) were increased due to a marked increase in fasting insulin levels." (PMID 30273374, 2018). "HFD-fed mice further showed elevated fasting blood glucose and insulin as well as homeostatic model assessment–insulin resistance (HOMA-IR) compared to CD-fed controls." (PMID 30022049, 2018). "pH is known to modify insulin activity, and that acidification is considered as a mechanism of insulin resistance." (PMID 30598026, 2018). "This differential response of gluconeogenesis and lipogenesis to insulin during insulin resistance has been termed “selective hepatic insulin resistance”." (PMID 30038596, 2018). "Leptin and insulin show a strong relationship, and leptin resistance is accompanied by hyperinsulinemia and insulin resistance." (PMID 29599686, 2018). "The treated mice developed severe hyperglycemia, obesity, impaired insulin secretion, and stable insulin resistance." (PMID 29659121, 2018). "Boys' triglycerides, insulin, homeostasis model assessment for insulin resistance (HOMA-IR) and systolic BP deteriorated at 24 months (P < 0.001, 0.004, 0.002, and 0.037, respectively)." (PMID 30333791, 2018). "Insulin resistance is a pathological condition that the insulin sensitive organ, such as liver and muscle, resist the action of insulin." (PMID 30081580, 2018). "Body weight, fasting plasma insulin, insulin resistance index, and lipid profiles were measured along with oral glucose tolerance tests (OGTTs)." (PMID 30302116, 2018). "To verify the improvement in insulin sensitivity by Ln4, we measured insulin resistance index and conducted oral glucose tolerance tests (OGTT) and insulin tolerance tests (ITT) in mice." (PMID 29783731, 2018). "Insulin resistance is a condition in which the target tissues of insulin such as skeletal muscle, adipose tissue, and liver show a reduction in their response to physiological concentrations of the insulin hormone." (PMID 30363988, 2018). "Several studies have shown that vaspin increases insulin secretion and ameliorates insulin resistance." (PMID 29891806, 2018). "Diabetes has a multifaceted pathogenesis that occurs either due to impaired insulin secretion or due to development of insulin resistance at target tissues and/or wide-ranging destruction of pancreatic β-cells." (PMID 30320139, 2018).
Insulin resistance (continued). "Insulin dysregulation, stemming from excessive insulin secretion and peripheral insulin resistance, is the main endocrinopathy proposed in EMS." (PMID 30001422, 2018). "Vitamin D significantly affects glucose metabolism, regulates exocytosis of insulin, directly affects stimulation of insulin receptors, improves intake of glucose in peripheral cells and regulates insulin resistance." (PMID 29760812, 2018). "Insulin plays a key role in normal learning and memory, and insulin resistance has been reported to affect cognition." (PMID 29330372, 2018). "More detailed models of insulin mediated cell signaling have been developed that represent the development of insulin resistance in various cell types as a function of inhibition of insulin signaling by multiple factors." (PMID 29444133, 2018). "The HOMA2-IR value of the NC group was within the insulin-sensitivity range (< 1.9), while it was significantly increased to the moderate insulin resistance range (> 2.9) in the pre-D group (p < 0.05)." (PMID 30011905, 2018). "By removing triggers for insulin secretion, thereby lowering insulin and insulin resistance, CR is interrupting that positive feedback loop." (PMID 29518898, 2018). "The rs9939609 FTO gene polymorphism was associated with certain obesity complications, such as high blood pressure, percentage body fat and fat mass, plasma insulin levels, and insulin resistance." (PMID 30338250, 2018). "Obesity was associated with higher basal levels of serum insulin (P < 0.05), plasma triacylglycerol (P < 0.01), plasma cholesterol (P < 0.01), and plasma CRP (P < 0.01), as well as increased insulin resistance determined by HOMA‐IR (P < 0.05)." (PMID 30009507, 2018). "Insulin resistance is a pathological condition involving a failed response to normal levels of insulin." (PMID 29973864, 2018). "We also observe increased AUC of glucose (p < 0.001) and insulin during oGTT, featuring a frame of hyperglycemia and hyperinsulinemia, suggesting insulin resistance." (PMID 29449893, 2018). "Insulin resistance is typically defined as decreased sensitivity to metabolic actions of insulin that promote glucose disposal." (PMID 29675020, 2018). "This is likely to be particularly important for the subset of mutants (e.g. I119M, K460E) where acute insulin stimulations studies are normal, as in this and other reports, but which confer extreme insulin resistance in vivo." (PMID 29700562, 2018). "Several insulin sensitizers (such as biguanides and thiazolidinediones) were considered as therapeutics for DM with insulin resistance." (PMID 30445954, 2018). "HOMA assesses beta cell function and insulin sensitivity in percentages and by imputing plasma glucose levels and insulin levels into the model can derive the estimated insulin resistance." (PMID 29410390, 2018). "HOMA-IR, HOMA-β, and ISI were calculated according to fasting blood glucose and basal insulin values in the evaluation of the degree of peripheral insulin resistance and islet β-cell function." (PMID 30374328, 2018). "Here, we review main findings on miRNA functions as modulators of insulin signaling in physiologic- or in T2D insulin resistance- status." (PMID 30469501, 2018). "Insulin resistance was induced in the preadipocytes by treating with dexamethasone and insulin for 60 h (eight days is required to obtain mature adipocytes under the culture conditions), a method shown to promote insulin resistance in this cell line." (PMID 29601521, 2018). "Potential approaches to reducing insulin resistance include weight reduction, as well as targeting renal sodium handling or improving insulin sensitivity." (PMID 29456896, 2018). "Insulin resistance is characterized by elevated circulating insulin and glucose due to impaired functioning of the insulin receptors." (PMID 30521580, 2018). "Type 2 diabetes is a heterogeneous syndrome that is related to both defective insulin secretion and peripheral insulin resistance." (PMID 30061862, 2018).
Insulin resistance (continued). "Metformin improved poor glycemic control as well as insulin resistance in adolescents with type 1 diabetes who were on high-dose insulin therapy." (PMID 29338714, 2018). "Specifically, 5-PAHSA treatment significantly increased insulin stimulated glucose uptake, thus improved insulin resistance induced by high insulin/TNF-α." (PMID 30666198, 2018). "Protein expression for Mfn1 (P < 0.001), PGC1α (P < 0.05), BNIP3 (P < 0.0001), and mitochondrial complexes I‐V (P < 0.01) was also increased by RYGB, and Mfn1 expression negatively correlated with body weight, insulin resistance, and fasting plasma insulin." (PMID 29464885, 2018). "In HF diet–fed mice, blood glucose and plasma insulin concentrations increased in comparison with the control group, and these mice had insulin resistance as determined by homeostasis model assessment of insulin resistance (HOMA-IR)." (PMID 29630667, 2018). "Most importantly, in the presence of rosemary extract the palmitate-induced insulin resistance was prevented and the insulin-stimulated glucose uptake was restored to levels comparable to the response seen with insulin alone." (PMID 30400151, 2018). "A feature of T2DM is a variable loss of peripheral insulin sensitivity (IS); in humans predominantly reflecting reduced efficacy of insulin signaling (‘insulin resistance’, IR) in skeletal muscle and liver." (PMID 29986096, 2018). "This is important because insulin levels can increase many folds with insulin resistance, while LH and ACTH levels are more stable." (PMID 29971102, 2018). "Ultimately, ectopic lipid deposition and increased expression of inflammatory mediators in the liver and skeletal muscle lead to impaired insulin signaling and exacerbate systemic insulin resistance." (PMID 30574122, 2018). "Obesity, coupled with insulin resistance increases insulin demand and hyperfunction of pancreatic beta cells resulting in their eventual dysfunction." (PMID 29534487, 2018). "In line with the observed peripheral insulin resistance, elevated brain insulin levels in our R6/2 mice were normalized after 2 weeks of co-administration of liraglutide and ghrelin." (PMID 29895889, 2018). "Insulin resistance is defined as the failure of cells to respond normally to insulin’s glucose-lowering effects." (PMID 29523782, 2018). "Data from studies regarding serum 25(OH)D, fasting blood glucose (FBG), hemoglobin A1c (HbA1c), fasting insulin and homeostasis model assessment of insulin resistance (HOMA-IR) were pooled." (PMID 29562681, 2018). "An improved glucose tolerance, accompanied by reduced serum insulin was found in S. spinosum treated mice, indicating that the extract affects the target tissues of insulin either by alleviating insulin resistance or by mimicking its action." (PMID 29768504, 2018). "These are thought to interfere with insulin signaling mediated glucose transport, and thus result in insulin resistance (IR) in skeletal muscle." (PMID 30344510, 2018). "Here, we want to further expand upon our previous findings where we established a relationship between FKBP51, glucocorticoids, insulin resistance and the impairment of insulin-stimulated glucose uptake in human adipose tissue." (PMID 30032404, 2018). "Insulin resistance is a condition in which a greater than normal amount of insulin is required to obtain a quantitatively normal metabolic response." (PMID 30151057, 2018). "The leptin-to-adiponectin ratio, as another measure of systemic insulin resistance, was elevated in 30-week-old B6-Tg(Ifi202b) mice and confirmed the impaired insulin sensitivity." (PMID 29478099, 2018). "In prediabetic subjects serum glucose begins to rise due to increase of insulin resistance and, as described in S7 Table, it is expected that serum glucose would be sensitive to changes in αdep_ffa which directly increases insulin resistance." (PMID 29444133, 2018).
Insulin resistance (continued). "We also observed a significant decrease in the level of fasting insulin and insulin resistance (IR) index in the metformin-donepezil group, with a lower CCA-IMT value than that in the acarbose-donepezil group after a year of treatment (P < 0.05)." (PMID 30100873, 2018). "Hepatic insulin resistance, or low insulin sensitivity, favors lipogenesis, and thus the increase of novo synthesis of triglycerides and a higher secretion of VLDL type V1 and V2 (triglyceride-rich lipoproteins, TRLs), as was observed in our results." (PMID 30201894, 2018). "Disruption of glucose homeostasis underlies the physiopathology of type 2 diabetes mellitus (T2DM), which results from both peripheral insulin resistance and altered insulin secretion by pancreatic β-cells." (PMID 29523782, 2018). "In various cell lines (e.g. hepatocytes, adipocytes, skeletal muscle), the PI3K/Akt intracellular pathway through which insulin exerts its effects breakdown with increasing insulin resistance (hyperinsulinaemia)." (PMID 29566712, 2018). "In T2DM, insulin resistance is characterized by a decrease in the insulin responsiveness of the target tissues of insulin, particularly in liver, fat, and skeletal muscles." (PMID 29799006, 2018). "Dysfunctional insulin signaling consequent to the gradual occurrence of insulin resistance potentially triggers several common pathological processes that underpin both T2DM and neurodegenerative disorders, including PD10,11,13,21." (PMID 30013201, 2018). "Currently, a set of indices called HOMA-IR and HOMA-β are used to represent insulin resistance and glucose-stimulated insulin response by β cells respectively." (PMID 30307959, 2018). "Han men had the highest insulin resistance while Kazak men had the highest insulin sensitivity among those three populations." (PMID 30193578, 2018). "Previous studies have reported that elevated blood pressure is related to the secretion of insulin and increasing the prevalence of insulin resistance." (PMID 29524187, 2018). "Insulin sensitizers targeting insulin resistance in the brain can therefore be potentially beneficial in the prevention of Alzheimer’s disease or dementia." (PMID 30262775, 2018). "Knowleret al. have recently demonstrated that a 24-weektraining period that included 30 minutes bicycling threetimes a week in PCOS women resulted in a significantdecrease in fasting insulin and insulin resistance." (PMID 29043706, 2018). "Transgenic overexpression of human RBP4 or injection of recombinant RBP4 in normal mice caused insulin resistance, whereas deletion of RBP4 enhanced insulin sensitivity." (PMID 30374329, 2018). "Insulin resistance is characterized by a reduced physiological response of target tissues to normal levels of insulin and results in decreased glucose utilization in muscle and fat, as well as increased gluconeogenesis in the liver." (PMID 30419056, 2018). "In two studies including patients with active IBD, increased insulin resistance and impaired beta cell function were found, while in the remission state normal insulin sensitivity was reported." (PMID 29576769, 2018). "Especially, TNF is known to trigger insulin resistance and was also highly elevated at an insulin resistant stage in liver and fat in the old HFD mice." (PMID 29426925, 2018). "While some studies have shown adiponectin to be positively correlated with total body fat, HDL and insulin levels, others suggest that adiponectin levels are reduced in people with insulin resistance, T2DM and lipodystrophy." (PMID 29746485, 2018). "In conclusion, the following metabolic factors have been shown to influence total sRAGE and individual sRAGE isoforms in Alzheimer's disease: elevated insulin, amylin, insulin resistance as described by HOMA-IR, obesity by BMI, and high fat mass." (PMID 29681765, 2018). "Insulin resistance is a condition in which elevated insulin levels are required to maintain normal blood glucose." (PMID 29801514, 2018).
Insulin resistance (continued). "We previously reported that epicatechin supplementation decreased plasma insulin and improved insulin resistance in this study." (PMID 29672527, 2018). "In the second mechanism, ROS negatively regulates the insulin pathway leading to reduced insulin secretion and consequently insulin resistance." (PMID 30563117, 2018). "Two clinical methods are typically used for improved blood sugar control: increased insulin delivery or decreased peripheral insulin resistance." (PMID 29951281, 2018). "There are a number of possible physiological reasons for increased glucose variability, including, but not limited to, insulin resistance and impaired insulin secretion." (PMID 30040822, 2018). "The fact that insulin sensitivity was unaffected by canrenoate, but was improved by fasudil indicates that vascular insulin resistance in db/db mice is ROCK-dependent and MR-independent." (PMID 29440699, 2018). "An important feature of insulin resistance is the attenuation of insulin-stimulated glucose uptake in adipocytes and increased hepatic glucose output." (PMID 30380669, 2018). "Accordingly, a higher degree of insulin resistance and impaired insulin secretion was recently found to characterize patients with GDM requiring pharmacotherapy." (PMID 29854820, 2018). "We found that EA improved insulin sensitivity and decreased insulin resistance as determined by kITT and HOMA-IR, respectively." (PMID 29693586, 2018). "Identification of normoglycemic, insulin-resistant patients presenting DKD support the role of insulin resistance as a contributing factor in the pathogenesis of DKD, as described in a recent case report." (PMID 29686650, 2018). "Insulin resistance can be demonstrated by postreceptor defects at various levels in the insulin signalling pathway." (PMID 29484207, 2018). "In this model, adipocytes secrete proinflammatory cytokines like TNF which is able to inhibit insulin signaling, leading to insulin resistance." (PMID 29482543, 2018). "Chemerin is associated with markers of the metabolic syndrome in clinical cohorts and is able to induce insulin resistance in mouse models, especially in skeletal muscle while acting as an insulin-sensitizing agent in adipocytes." (PMID 29915268, 2018). "The importance of insulin to brain function is demonstrated by data showing impairment to cognition in conditions of insulin resistance such as type 2 diabetes." (PMID 29342865, 2018). "Altogether, HSD reduces the peripheral IIS, either via decreased production of insulin, or via insulin resistance." (PMID 29954158, 2018). "Insulin resistance is defined as an experimental or clinical condition in which insulin exerts a biological effect lower than expected." (PMID 30170598, 2018). "We further identify a rare human CRLS1 variant associated with insulin resistance and show that adipose CRLS1 levels positively correlate with insulin sensitivity." (PMID 29861389, 2018). "Studies in animal models of exercise suggest that increased physical activity can improve insulin sensitivity in adipose tissue, skeletal muscle, and endothelium, which are major contributors to systemic insulin resistance in individuals with type 2 diabetes." (PMID 30324108, 2018). "Changes in insulin status have subsequently been shown to alter microvascular recruitment where hyperinsulinemia stimulates total blood flow and with insulin resistance this mechanism is impaired." (PMID 29723218, 2018). "For example, peripheral insulin resistance primarily occurs in muscle and adipose tissue and is characterized by disturbed insulin-mediated stimulation of glucose uptake and utilization but increased fat decomposition of adipose tissue." (PMID 30692925, 2018). "During insulin resistance, suppression of hepatic glucose synthesis by insulin is blunted and the persistence of hepatic glucose output leads to postprandial hyperglycemia." (PMID 30038596, 2018).